RNU6-746P (RNA, U6 small nuclear 746, pseudogene)
Gene: Small nuclear RNA gene on chromosome 4 (55,294,490 to 55,294,598, forward strand). Ensembl gene ENSG00000206839.
Homologues: Orthologues: chimpanzee U6 (99% identical), macaque U6 (98% identical), rabbit U6 (83% identical). Paralogues in human: RNU6-1145P (87% identical), RNU6-15P (87% identical), RNU6-188P (87% identical), RNU6-1 (85% identical), RNU6-1024P (85% identical), RNU6-1060P (85% identical), RNU6-116P (85% identical), RNU6-1316P (85% identical), RNU6-19P (85% identical), RNU6-2 (85% identical), RNU6-21P (85% identical), RNU6-35P (85% identical), and 1281 more.